IL17A (interleukin 17A)
Diseases named in the same sentence as IL17A in open-access papers (continued):
Sharing a sentence is not in itself a finding about the gene and the disease.
systemic lupus erythematosus (continued). "Up-regulated cyclic adenosine 5'-monophosphate response element modulator α (CREMα) which can inhibit IL-2 and induce IL-17A in T cells plays a critical role in the pathogenesis of systemic lupus erythematosus (SLE)." (PMID 27904655, 2016). "Double-negative (DN) T cells are known to produce both IFN-γ and IL-17A in Fcgr2b-deficient lupus mice." (PMID 38886451, 2024). "Likewise, a significant inhibition of IL-17A production was obtained in a study performed on a mouse model with lupus, a chronic inflammatory disease with high production of IL-17A and treated with aconitine (alkaloid)." (PMID 35468134, 2022). "These IL-17A+ subpopulations are antigen specific, given that tetramer studies have identified RORγt+ IL-17A-producing T cells that are specific for U1-70 in humans and lupus-prone mice." (PMID 35620115, 2022). "Animal experiments have shown that the knockout of IL‐17A gene in lupus mice leads to a decrease in the number of peripheral blood B cells and serum total immunoglobulin G (IgG) levels, suggesting that IL‐17A participates in the pathogenesis of SLE by enhancing the humoral immune response." (PMID 35634952, 2022). "Reducing IL-17A alleviates the condition of patients with lupus." (PMID 36536372, 2022). "In addition, IL-17A can sustain plasma cell response and exacerbate the development of systemic lupus erythematosus (SLE)." (PMID 34122457, 2021). "Thus, the DNA vaccine for IL-17A significantly improved survival while sustaining anti-IL-17A antibody titers in lupus-prone mice." (PMID 32059488, 2020). "In addition, SHP2 inhibition reduced the proliferation of cultured human lupus T cells and decreased the production of IFN-γ and IL-17A/F in vitro, suggesting integral involvement of SHP2 in human lupus-associated immunopathology." (PMID 32973676, 2020). "Moreover, activated memory T cells from NZM WT lupus mice produce the proinflammatory cytokine IL-17A." (PMID 32870819, 2020). "Here we show reduced expression of the transcription factor RFX1 in CD4+ T cells from patients with systemic lupus erythematosus, which leads to IL-17A overexpression through increased histone H3 acetylation and decreased DNA methylation and H3K9 tri-methylation." (PMID 29422534, 2018). "As circulating IL-17A has been associated with immune complex deposition and complement activation in kidneys in a mouse model of lupus, it is quite likely that reduction of IL-17 in the bloodstream has a systemic mechanism that participates in the reduction of renal inflammation." (PMID 27278657, 2016). "Besides patients with lupus having abnormally high levels of IL-17A along with IFN-γ are reported in previous studies which have shown that the increased levels of serum IL-17A act as potent inflammatory responses." (PMID 27738386, 2016). "Concordantly, inhibition of IL-17A can decrease the manifestations of lupus." (PMID 27904655, 2016). "Conversely, studies have also found that in systemic lupus erythematosus (SLE), loss of PGRN reduces Th1, Th17, IFN-γ, and IL-17A levels, whereas it increases Th2, Treg, Breg, IL-4, and IL-10 levels." (PMID 40290306, 2025). "Studies investigating the pathological roles of IL-17 in systemic lupus erythematosus (SLE) suggest that IL-17A is a promising therapeutic target for this condition." (PMID 40977724, 2025). "In this review, we will focus on the pathophysiologic role of IL-17A in three major systemic autoimmune diseases including systemic lupus erythematosus (SLE), Sjögren syndrome (SS), and systemic sclerosis (SSC)." (PMID 35620115, 2022). "Overproduction of cAMP-responsive element modulator α (CREMα) in total T cells from patients with systemic lupus erythematosus (SLE) can inhibit IL-2 and increase IL-17A." (PMID 36536372, 2022).
systemic lupus erythematosus (continued). "Preclinical studies that have hinted at involvement of IL-17A in SLE pathology indicate that the absence of IL-17 in experimental lupus models is associated with inhibition of autoantibody formation targeting DNA, RNP, and chromatin and, even more striking, lupus nephritis." (PMID 35620115, 2022). "For example, while maternal serum IL-17A levels of 1–2 pg/mL are considered normal, levels of up to 10–30 pg/mL are seen in pregnancies complicated with systemic lupus erythematosus (SLE)." (PMID 34203644, 2021). "In terms of the functional importance of IL-17A in SLE and lupus nephritis, the induction of SLE by pristane in IL-17-sufficient wild-type mice did not occur in IL-17A-deficient mice, which were protected from the development of lupus autoantibodies and glomerulonephritis." (PMID 32059488, 2020). "Similar to coronary atherosclerosis, decreased RFX1 expression in CD4+ T cells from patients with systemic lupus erythematosus induces histone H3 acetylation and reduces DNA methylation and H3K9 trimethylation, leading to IL-17A overexpression." (PMID 41425715, 2025). "In disease models of systemic lupus erythematosus, SLAMF6 promotes the differentiation of T cells into Th17 cells and promotes the recruitment of RORγT to the IL-17A promoter." (PMID 39354345, 2024). "In patients with systemic lupus erythematosus (SLE), peripheral blood neutrophils exhibit increased NETosis, with IL-17A and tissue factor (TF) modulating the composition of the produced NETs." (PMID 39430569, 2024). "IL-17–producing T cells have been identified in kidney and skin lesions of patients with lupus, with 1 study of patients with DLE identifying IL-17A as highly expressed in both serum and damaged skin tissue." (PMID 37526979, 2023). "We found that in the pristane-induced lupus mouse model, mice fed with LID showed the fewer frequency and number of CD4+ IL17A+ Th17 cells and the lower ratio of Th17/Treg cells compared with the ND controls." (PMID 35296076, 2022). "John’s wort) proved effective in significantly reducing the serum level of IFN-g, IL-17A, IL-1b, TNF-a, and IL-6 in lupus-prone mice." (PMID 35431950, 2022). "In lupus-prone mice, IL-23 has been identified as an important driver of DNT expansion and IL-17A production." (PMID 35620115, 2022). "RFX1 downregulation causes CD11a, CD70 and IL17A overexpression by reducing DNA methylation and increasing H3 acetylation levels in the promoter region of CD11a, CD70 and IL17A in the CD4+ T cells of systemic lupus erythematosus (SLE) patients, which contributes to autoimmune responses." (PMID 31737059, 2019). "Although preliminary investigations are lacking, it is crucial to evaluate the potential role of IL-17A in thrombotic occurrences among lupus patients." (PMID 40977724, 2025). "Third, basophil depletion dramatically dampened both constitutive and PMA-ionomycin-induced IL-21 and IL-4 productions by TFH cells only in the lupus-like context, without significantly influencing their IFNγ or IL-17A production abilities." (PMID 38649353, 2024). "Similarly, B6.lpr−/− lupus-prone mice devoid of IL-23R abrogated the development of LN, coupled with a reduction of the number of DNTC, IL-17A-producing cells in lymph nodes and anti-dsDNA antibody production." (PMID 35326431, 2022). "The alterations of serum IL-17 after vaccination were not significantly different because the plasma IL-17A concentration was not as high as in spontaneous lupus-prone mice." (PMID 32059488, 2020). "Collectively, in lupus-prone mice, U1-70–specific DN T cells respond to U1-70 and produce IL-17A in MHC class I, but not class II-dependent manner." (PMID 32503973, 2020). "Serum proinflammatory cytokines, including IL-17a, IFN-γ, IL-6, TNF, and IL-2, were significantly increased, while the anti-inflammatory cytokine IL-10 was significantly decreased in sodium chloride-pretreated BMDC-ALD-DNA-induced lupus mice." (PMID 32296043, 2020).
systemic lupus erythematosus (continued). "Further, in the NZB/NZW lupus model, nephritis was not affected by neutralization of IL-17A, whereas neutralization of IFN-γ ameliorated disease severity." (PMID 31297111, 2019). "RFX1 downregulation caused CD11a, CD70, and IL17A overexpression by reducing DNA methylation and increasing H3 acetylation levels in the promoter region of CD11a, CD70, and IL17A in the CD4+ T cells of systemic lupus erythematosus (SLE) patients, which contributed to autoimmune responses." (PMID 30857550, 2019). "In IL-23R KO/lpr mice, which do not develop lupus, the total number of DN T cells as well as the total number of IL-17A producing DN T cells and CD4+ T cells was decreased." (PMID 30858513, 2019). "Our data revealed amelioration of BTN3A1‐induced lupus‐like changes, such as improved degree of renal injuries and reduced percentage of CD3+, CD8+ T cells, Th1, Th2, Th17 cells, upregulated percentage of Treg cells, and lower expression of IL‐4, IL‐6, IL‐10, IL‐17A, IFN‐γ, TNF‐α, and dsDNA." (PMID 40959207, 2025). "However, the therapeutic targeting of IL-17A with ixekizumab has not been documented in clinical practice for lupus." (PMID 39339212, 2024). "Similarly, FcγRIIb−/− lupus mice treated with etanercept upregulated cancellous bone volume and cortical thickness and downregulated expression of osteoblast marker genes (OSX, Collagen type I α 1) and serum levels of TNFα, IFNγ, IL-6, and IL-17A." (PMID 38164134, 2023). "Some reports suggest that estrogen receptor α (ERα) signaling increases IL-17A production in Th17 cells by upregulating IL-23R expression in a Let-7f-dependent manner, and this might be a reason for the increasing prevalence of systemic lupus erythematosus (SLE) and multiple sclerosis in women." (PMID 33816637, 2021). "In addition to CD4+ Th17 cells, IL-17A is produced by γδ T cells, NK cells, and is secreted by CD3+ (CD4-/CD8-) cells infiltrating salivary glands in Sjögrens syndrome and in the plasma from those with systemic lupus erythematosus." (PMID 35003055, 2021). "Likewise, neutralization of IL-17A by anti-IL-17A antibodies had no significant impact on the extent of nephritis in New Zealand Black/New Zealand White (NZB/NZW) F1 lupus-prone mice." (PMID 32183259, 2020). "Proinflammatory immune cells, including B cells, plasma cells, CD4+ T cells, Tfh cells, GCB cells, IL-17a+ T cells, and IFN-γ+ T cells, were increased in sodium chloride-pretreated BMDC-ALD-DNA-induced lupus mice compared to those in control BMDC-ALD-DNA-induced lupus mice." (PMID 32296043, 2020). "However, a study using lupus-prone mice demonstrated that pharmacological inhibition and genetic ablation of IL-17A did not improve clinical manifestations, including survival rate, glomerulonephritis, and autoantibody production." (PMID 33597953, 2020). "Moreover, they reported no remarkable variation in the serum levels of IL-17A following the intravenous injection of allogeneic UC-MSCs into patients suffering from active and refractory systemic lupus erythematosus (SLE)." (PMID 32411794, 2020). "In systemic lupus erythematosus (SLE), RFX1 downregulated IL17A, CD70, and CD11a expression by recruiting DNMT1, HDAC1, and SUV39H1 to alter epigenetic modifications in CD4+ T cells from patients with lupus." (PMID 30857550, 2019). "The autoimmune SmD66-80 T cells in lupus patients are not biased toward IL-17a expression, indicating that these autoimmune CD4+ T cells may not only express IL-17a, but a mixture of other cytokines." (PMID 36389825, 2022). "More importantly, we could show that both IFN-γ and IL-6, two cytokines involved in lupus pathogenesis, significantly down-regulated Trap1 expression in spleen cells after in vitro culture, whereas no change was observed with IFN-α or IL-17A." (PMID 33746957, 2021).
periodontitis (359 papers, 2008 to 2026). An acute or chronic inflammatory process that affects the tissues that surround and support the teeth. "In this regard, some gene variants of the IL‐23/IL‐17 axis and its receptors have been analyzed in periodontitis, but only associations with IL‐17A and IL‐17F have been found." (PMID 41536464, 2026). "Six (33.3%) studies found an association between the IL‐17A: 197 G/A (rs2275913) genetic variant and peri‐implantitis and periodontitis." (PMID 39887950, 2025). "In our experiments, we observed elevated levels of serum pro-inflammatory cytokines (IL-17A, IL-1β, IL-6, IL-8) associated with periodontitis." (PMID 40732209, 2025). "Regarding the IL‐17A gene, twelve studies evaluated the rs 2275913 upstream variant in 1791 individuals with periodontitis and in 15 individuals with peri‐implantitis." (PMID 39887950, 2025). "In this disorder, periodontitis has been associated with a marked upregulation of IL-17A and other related cytokines, as well as chemokines responsible for neutrophil recruitment (CXCL2, CXCL5)." (PMID 41462866, 2025). "Some in vivo investigations also indicate that IL-17 promotes pathological bone loss in experimental periodontitis, and some research validated the therapeutic efficacy of IL-17A antibodies in experimental periodontitis." (PMID 40248692, 2025). "One study (5.5%) found an association between the IL‐17A: rs10484879 variant and peri‐implantitis and periodontitis." (PMID 39887950, 2025). "Recently, it has been reported that continuous administration of IL-17A-neutralizing antibodies to the periodontal region can inhibit inflammatory bone loss in mice with experimental periodontitis in an animal study." (PMID 37623290, 2023). "In the periodontitis rat model, IL-17A was linked to increased alveolar bone loss and a rise in osteoclasts." (PMID 36902030, 2023). "Blocking of IL-17A in rats with induced periodontitis significantly reduced the alveolar bone loss osteoclast number." (PMID 36902030, 2023). "This review seeks to present the current knowledge on oral dysbiosis and its prevention, as well as the underlying role of IL-17A in periodontitis induced by oral dysbiosis and its impact on systemic inflammatory disease." (PMID 37623290, 2023). "Periodontitis-associated upregulation of IL-17A and RANKL is mediated through eliciting receptors expressed on myeloid cells-1 (TREM-1)." (PMID 36902030, 2023). "Our data showed that IL-17A also linked the microbiota of periodontitis and the worse outcome of ischemic stroke." (PMID 35663549, 2022). "IL-17A plays a vital role in the process of periodontitis because of its close association with periodontal bacteria." (PMID 35663549, 2022). "Both IL-17A and IL-18 have been proposed to be biomarkers for periodontitis and were linked to the pathogenesis of type 2 DM as well." (PMID 32053656, 2020). "Salivary IL-17A was strongly associated with periodontitis, whereas salivary IL-18 was associated with FPG and serum IL-18 was associated with HbA1C." (PMID 32053656, 2020). "Despite the high expression of IL-17A in inflamed gingiva, periodontitis-induced bone loss in Il17a–/– mice was comparable with that in wild-type mice." (PMID 29453398, 2018). "Our group already reported that the AA genotype and A allele for IL17A were associated with susceptibility to chronic periodontitis in South Brazil, highlighting their involvement in a chronic inflammatory condition." (PMID 29849482, 2018). "We first investigated pathogenic T cell populations in periodontitis by evaluating IL-17A and IFN-γ producing CD4+T cells in CP patients." (PMID 28229025, 2017). "The critical role of IL-17 in mediating bone loss was confirmed using a ligature model of periodontitis where local administration of mAbs to IL-17A or IL-17F inhibited bone destruction." (PMID 28497028, 2017).
periodontitis (continued). "In these patients from Southern Brazil, the IL17A rs2275913 polymorphisms, IL17A AA genotype, and the A allele were associated with a susceptibility to chronic periodontitis." (PMID 26339129, 2015). "Furthermore, studies have demonstrated a positive correlation between probing depth, clinical attachment loss, and IL-17A expression levels in the gingiva of patients with chronic periodontitis." (PMID 40248692, 2025). "Moreover, genetic variants such as the IL-17A −197 A allele have been associated with increased IL-17 production, poor glycemic control, and heightened risk of comorbidities such as periodontitis in T1D." (PMID 40804870, 2025). "In addition to this, it has been observed that the serum levels of IL‐17A in chronic periodontitis patients with allele A are greater than in patients with allele G." (PMID 39887950, 2025). "However, increased levels of salivary IL-17A, IL-18 and IL-1B levels were associated with periodontitis." (PMID 38756445, 2024). "Moreover, further analysis demonstrated a high correlation between IL-17A+IL-17F- Th17 cells and attachment loss or probing depth suggesting that these IL-17 producing cells are involved in the pathogenesis of periodontitis." (PMID 39253090, 2024). "OSA may increase the risk of developing periodontitis due to increase of IL-1β and IL-6 in saliva and IL-6, IL-17A and IL-33 in GCF that share the activation of the osteoclastogenesis." (PMID 36967976, 2023). "Furthermore, patients with diabetes mellitus and chronic periodontitis have increased salivary levels of IL-17A compared with healthy controls, suggesting that elevated IL-17A levels are a risk factor for chronic periodontitis in these patients." (PMID 37623290, 2023). "In animal experiments, Pacheco recently found that continuous delivery of IL-17A neutralizing Antibodies in local periodontal region could limit inflammatory bone loss in experimental periodontitis mice." (PMID 35371044, 2022). "IL17A polymorphism was significantly associated with the counts of T. forsythia and T. denticola in healthy Czech patients with periodontitis and in those with type 1 diabetes mellitus and periodontitis, respectively." (PMID 35122548, 2022). "Finally, we tested the importance of IL-17A-producing cells in the association between periodontitis salivary microbiota and ischemic stroke using IL-17A knockout mice." (PMID 35663549, 2022). "This study also suggested that anti-IL-17A Abs decreased IL-6 gene expression in gingival tissue of periodontitis-induced mice and suppressed alveolar bone loss and osteoclastic activity; hence, IL-17A Abs might be an effective treatment for periodontitis." (PMID 34445604, 2021). "In this study, experimental periodontitis was associated with the progressive and increased presence of Th17 and Treg-related mediators in the gingiva (IL-6, IL-17A, IL-17F, RANKL, IL-10, TGF-β and GITR; P < 0.05), and the proliferation of both Treg and Th17 cells in cervical lymph nodes." (PMID 33149125, 2020). "Corroborating our data, previous studies have documented increased level of IL-17A in saliva, serum, and gingival crevicular fluid (GCF) in periodontitis compared to healthy subjects and also reported important role of IL-17 in gingival inflammation and bone loss." (PMID 29670909, 2018). "In view of the results indicating higher frequency of AG/AA alleles among the IL-17A G197A genotypes of patients with periodontitis, we further investigated whether some of these polymorphisms were associated with worse clinical periodontal parameters." (PMID 23304063, 2012). "The purpose of the current study was to determine whether the IL-17A G197A and IL-17F C7488T polymorphisms were associated with increased susceptibility to periodontitis." (PMID 23304063, 2012).